JUNB (JunB proto-oncogene, AP-1 transcription factor subunit)
Diseases named in the same sentence as JUNB in open-access papers (continued):
Sharing a sentence is not in itself a finding about the gene and the disease.
skin inflammation (2 papers, 2018 to 2020). "JunB deficiency in basal progenitors results in a dermatitis-like syndrome resembling seborrheic dermatitis harboring structurally and functionally impaired sebaceous glands with a globally altered lipid profile." (PMID 30143626, 2018). "More importantly, adult (9–12 weeks) JunB cKO mice suffered from symptoms like itching and skin inflammation on facial and neck skin." (PMID 30143626, 2018). "In contrast to the effects of dithranol in the c-Jun/JunB model and mouse-tail test, this agent had no therapeutic capacity in the immunologically mediated imiquimod (IMQ) mouse model, which is often referred to as a psoriatic-like skin inflammation model." (PMID 32484435, 2020).
squamous cell carcinoma (2 papers, 2014 to 2017). A carcinoma arising from squamous epithelial cells. "Consistent with JunB expression status in squamous cell carcinoma, c-Jun is remarkably reduced in human ESCC." (PMID 24796531, 2014).
systemic sclerosis (2 papers, 2021 to 2023). A chronic disorder, possibly autoimmune, marked by excessive production of collagen which results in hardening and thickening of body tissues. "The defective degradation of JunB in patients with systemic sclerosis contributes to the overproduction of type I collagen and the development of dermatofibrosis." (PMID 33802099, 2021).
T cell lymphoma (2 papers, 2014 to 2022). "The common related pathological pathways for both JUNB and JUND are oxidative stress and T cell lymphoma." (PMID 35341155, 2022). "The genotypes of the T-cell lymphomas isolated from 10–18 week old mice were JunB wildtype (NPM-ALK/JunB+/+), JunB hemizygous (NPM-ALK/JunB+/Δ) and lacked JunB completely (NPM-ALK/JunBΔ/Δ)." (PMID 25013898, 2014).
T-cell acute lymphoblastic leukemia (2 papers, 2023). Acute lymphoblastic leukemia of T-cell origin. "JunB was identified as the target gene of miR-149*, an oncogenic miRNA, in T-cell acute lymphoblastic leukemia, suggesting that JunB may be a tumor suppressor." (PMID 37731821, 2023).
thyroid cancer (2 papers, 2020). "This region includes several genes, such as ICAM1 gene, which is overexpressed in thyroid cancer cells, and the JunB proto-oncogene, AP-1 transcription factor subunit (JUNB)." (PMID 33218058, 2020). "Components of the AP-1 transcription factor, including JUN, JUNB, FOS, FOSB, were enriched in association with TTP as a conserved co-regulated group of genes and were significantly downregulated in breast, liver, lung, kidney, and thyroid carcinomas." (PMID 32545247, 2020).
tongue cancer (2 papers, 2014 to 2015). A malignant neoplasm affecting the tongue. "Both tongue cancer cell lines also showed similar functional AP-1 complex formation mainly by c-Fos and Fra-2 along with JunB and JunD though they differ in their extent of involvement." (PMID 26581505, 2015). "Furthermore, the expression of JunB is enhanced in 4-nitroquinoline 1-oxide induced rat tongue cancers." (PMID 24466237, 2014). "Both HPV+ve and HPV−ve tongue cancer cell lines also provided similar results except that it showed preferential participation of JunB instead of c-Jun observed in HPV negative tongue cancer tissues." (PMID 26581505, 2015).
ZIKV infection (2 papers, 2017 to 2024). "In contrast, ZIKV infection increased the expression of regulators of cell survival, apoptosis and differentiation, such as pim2, cbx7a, as well as components of the activator protein 1 (AP-1) family members (jun, junB, fosab)." (PMID 39621753, 2024). "This study noted the induction of ATF3, EGR1, JUNB, IRF7, ISG15, HERC5/6, additional ISGs, chemokines CCL5 and CXCL10, prosurvival responses, and decreased proapoptotic genes, similar to gene induction levels we found to be induced by ZIKV infection of hBMECs (GEO GSE98889)." (PMID 28698279, 2017).
Achalasia (1 paper, 2023). A disorder of esophageal motility characterized by the inability of the lower esophageal sphincter to relax during swallowing and by inadequate or lacking peristalsis in the lower half of the body of the esophagus. "Analysis of DEGs showed the common upregulations of SFPQ, KLF2, and CYBA and common downregulations of JUNB, FAM118A, and C21orf33 in peripheral blood lymphocytes of achalasia." (PMID 37542039, 2023).
adenomyosis (1 paper, 2020). The growth of endometrial tissue inside the muscular wall of the uterine corpus. "Isolated total RNA from endometrial biopsy samples collected during the window of receptivity were used to verify whether selected candidate genes LIF, SOCS3, FOS, JUNB, IL6 and IL10 were differentially expressed between adenomyosis and control groups." (PMID 32933042, 2020). "Despite LIF, IL6, IL10, JUNB, FOS and SOCS3 showing no statistically altered expression patterns between study groups, their lower expression levels were observed in the adenomyosis group." (PMID 32933042, 2020).
AIDS (1 paper, 2024). A syndrome resulting from the acquired deficiency of cellular immunity caused by the human immunodeficiency virus (HIV). "Specifically, in JunB deficient mice, T cells become more sensitive to T cell receptor mediated apoptosis, which could potentially exacerbate the progression of AIDS in an HIV infected patient." (PMID 38835488, 2024).
asthma (1 paper, 2018). "JunB has been shown to be important for the development of murine experimental asthma, due to its role in Th2 cell differentiation and the production of Th2 cytokines." (PMID 30233597, 2018).
atopic dermatitis (1 paper, 2007). "IL-4 has been reported to stimulate expression of JunB in peripheral blood monocytes from patients with atopic dermatitis." (PMID 17319946, 2007).
bladder tumors (1 paper, 2022). "Hence, in the study, we analyzed the molecular characteristics of the gene JUNB in ten muscle-invasive bladder tumors." (PMID 35812726, 2022).
Candida infection (1 paper, 2022). "Therefore, during Candida infection, the regulation of JUNB may affect Treg cells in resisting Candida infection." (PMID 35314002, 2022).
cardiomyopathy (1 paper, 2025). A disease of the heart muscle or myocardium proper. "The transcription factors FOS, FOSB, and JUNB may help prevent adverse events such as cardiac fibrosis in cardiomyopathy." (PMID 40717095, 2025). "Hence, it is plausible that the release of TFs FOS, FOSB, and JUNB by C6 S100A4+ SMCs contributes to exacerbating cardiomyopathies, potentially through the induction of cardiac fibrosis and inflammation." (PMID 40717095, 2025).
cerebral malaria (1 paper, 2025). A sequestration of Plasmodium falciparum in the brain, which can cause coma and/or seizures. "Notably, myeloid-specific JUNB deletion in cerebral malaria models reduces IL-1β/TNF production and shifts macrophages toward a regulated phenotype, improving survival, a finding that dovetails with our observation that JUNB silencing suppresses M1 polarization and NF-κB activation." (PMID 40917776, 2025).
childhood asthma (1 paper, 2022). "Concretely, ERK1/2 inducible proteins Jun b proto-oncogene (JunB) mediates ERK1/2 activation via the AP-1 complex, which increases the expression of several Th2 cytokines and drives Th2 cell differentiation, causing childhood asthma." (PMID 35656293, 2022).
chondrosarcoma (1 paper, 2017). A malignant cartilaginous matrix-producing mesenchymal neoplasm arising from the bone and soft tissue. "Another article performed a genome-wide cDNA expression analysis and found that Ollier's disease and solitary enchondromas revealed similar expression profiles; JunB may be of diagnostic relevance to grade I chondrosarcomas." (PMID 28410203, 2017).
chronic myelomonocytic leukemia (1 paper, 2010). A myelodysplastic/myeloproliferative neoplasm which is characterized by persistent monocytosis, absence of a Philadelphia chromosome and BCR/ABL fusion gene, fewer than 20 percent blasts in the bone marrow and blood, myelodysplasia, and absence of PDGFRA or PDGFRB rearrangement. "Mice lacking the AP-1 transcription factor JunB in hematopoietic cells develop a myeloproliferative disorder (MPD) that accurately reproduces important clinical aspects of human leukemias including chronic myelogenous leukemia (CML) and chronic myelomonocytic leukemia (CMML)." (PMID 20098702, 2010).
classical Hodgkin lymphoma (1 paper, 2025). "However, the mutated genes, such as SOCS3, JUNB, IRF1 and ITPKB, were not the typical targets known from classical Hodgkin lymphoma (cHL)." (PMID 40670673, 2025).
clear cell renal cell carcinoma (1 paper, 2016). "We previously reported that the pVHL‐atypical PKC‐JunB pathway contributed to promotion of cell invasiveness and angiogenesis in clear cell renal cell carcinoma (ccRCC), and we detected chemokine (C‐C motif) ligand‐2 (CCL2) as one of downstream effectors of JunB." (PMID 27666332, 2016).
cocaine addiction (1 paper, 2022). "In addition, decades of research on cocaine addiction have revealed that several genes such as deltaFosB, Dlg1, JunB, and AMPA receptor subunit GluR221,22, are implicated in cocaine addiction." (PMID 35469040, 2022).
colon adenocarcinoma (1 paper, 2021). "In contrast, colon adenocarcinoma showed a significant enrichment of TFs such as CDX2 (26.5%), CDX1 (24%), HOXA13 (22%), HNF4G (37.2%), and TCF4 (36%) in gained peaks; and FOS::JUNB (45.4%), FOS::JUND (47.5%) and JUNB (46.3%) in lost peaks." (PMID 34090364, 2021).
diabetic foot ulcer (1 paper, 2025). "They unveiled the potential association between important ceRNAs (JUNB, GATA3, hsa_circ_0049271, and hsa_circ_0074559) and infiltrating immune cells (CD8 + T cells and monocytes) with a diabetic foot ulcer." (PMID 40419622, 2025).
diffuse large B-cell lymphoma (1 paper, 2024). "AZD4573 could downregulate multiple oncoproteins (MYC, Mcl-1, JunB, PIM3) and deregulate PI3K pathways in diffuse large B-cell lymphoma (DLBCL)." (PMID 38566153, 2024).
E. coli infection (1 paper, 2017). "Among these, only the factors JUNB and EGR1 were also regulated during the E. coli infection." (PMID 28684793, 2017).
endothelial dysfunction (1 paper, 2023). In vascular diseases, endothelial dysfunction is a systemic pathological state of the endothelium (the inner lining of blood vessels) and can be broadly defined as an imbalance between vasodilating and vasoconstricting substances produced by (or acting on) the endothelium. "The “anti‐endothelial dysfunction (anti‐ED)” list consists of 31 genes that significantly ameliorate the ED phenotypes, with JUNB, NR4A3, SALL4, CSF2 and HEY1 being the top hits." (PMID 38031960, 2023).
gallbladder cancer (1 paper, 2015). "Here we showed that PDK1 stimulated cell proliferation, invasion and metastasis in gallbladder cancer (GBC), by inducing JunB and epithelial–mesenchymal transition." (PMID 26318166, 2015).
Helicobacter pylori (1 paper, 2016). "Within T cells, Helicobacter pylori (Hp) infection and high-salt dietcan up-regulated SGK1 expression and in turn enhance expression of Lnc-SGK1 through JunB activation." (PMID 26942879, 2016).
HIV-1 infection (1 paper, 2024). The type species of lentivirus and the etiologic agent of acquired immunodeficiency syndrome (AIDS). "Sequencing of the surviving cell population led to the identification of a previously unidentified host factor, JunB, as necessary for HIV-1 infection." (PMID 38835488, 2024). "Of particular importance, we attempted to generate a JunB KO cell line in the CEM-T4 cell line to better model the impact of JunB KO on HIV-1 infection in a more relevant T cell line." (PMID 38835488, 2024).
idiopathic pulmonary hypertension (1 paper, 2024). "Furthermore, the results indicated an increase in the expression of DEGs related to the reactive oxygen species pathway (NDUFB4, PDLIM1, GPX4, and JUNB), and a decrease in the expression of SOD, which has an antioxidant function, in the presence of idiopathic pulmonary hypertension." (PMID 38586587, 2024).
IgA nephropathy (1 paper, 2021). "Compared with the mesangial of donor, the gene CLIC1 and RPS26 were up‐regulated in mesangial of IgA nephropathy(IgAN), whereas the gene JUNB was up‐regulated in podocyte of IgAN in comparison with that of donor." (PMID 33754492, 2021).
inflammatory bowel disease (1 paper, 2023). A spectrum of small and large bowel inflammatory diseases of unknown etiology. "JunB also promotes Treg-mediated immunosuppression, and the absence of JunB leads to inflammatory disorders, such as inflammatory bowel diseases." (PMID 37731821, 2023).
inflammatory breast carcinoma (1 paper, 2023). An advanced, invasive breast adenocarcinoma characterized by the presence of distinct changes in the overlying skin. "Intriguingly, the expression of JunB is significantly upregulated in patients with inflammatory breast cancer compared to those with non-inflammatory breast cancer, suggesting that JunB may play a regulatory role in the underlying inflammatory processes in." (PMID 37731821, 2023).
intervertebral disc degeneration (1 paper, 2024). "The genes that are upregulated in the IVDD group, such as JUNB, SYDE1, ADAM8, and MAFB, are primarily involved in inflammatory responses, extracellular matrix remodeling, and cellular stress responses, which are processes known to be associated with intervertebral disc degeneration." (PMID 39430414, 2024).
ischemia (1 paper, 2025). A hypoperfusion of the BLOOD through an organ or tissue caused by a PATHOLOGIC CONSTRICTION or obstruction of its BLOOD VESSELS, or an absence of BLOOD CIRCULATION. "Among these, the markers that appear earliest in ischemia are connexin 43, JunB, and cytochrome c, which become positive within 30 min of ischemia onset." (PMID 40361926, 2025).
Listeria monocytogenes infection (1 paper, 2021). "The loss of c-Jun and JunB in DC progenitors diminishes the CD8α cDC1 pool and thus confers resistance to Listeria monocytogenes infection." (PMID 33758366, 2021).
liver fibrosis (1 paper, 2023). "The preference of JunB for ECM cluster genes (cluster 2) confirmed a recently described positive correlation of JunB levels with liver fibrosis in human and murine samples in hepatic stellate cells." (PMID 37415213, 2023).
lung squamous cell carcinoma (1 paper, 2023). "KLF6 and JUNB were downregulated in LUAD and lung squamous cell carcinoma (LUSC) (p < 0.05)." (PMID 37405258, 2023).
malaria (1 paper, 2013). Malaria is a serious and sometimes fatal disease caused by a parasite that commonly infects a certain type of mosquito which feeds on humans. "In contrast, many macrophage inhibition-related genes were up-regulated after malaria, including haem oxygenase 1 (HMOX1), JunB, and IRF1." (PMID 24188121, 2013).
megakaryocytic acute leukemia (1 paper, 2013). "JunB is a direct target of serum response factor (SRF), a ubiquitous transcription factor involved in smooth muscle proliferation, differentiation and contractility, along with megakaryocytic acute leukemia (MAL), an SRF coactivator." (PMID 23308222, 2013).
myeloid leukemia (1 paper, 2012). A clonal proliferation of myeloid cells and their precursors in the bone marrow, peripheral blood, and spleen. "The connection between M-CSF and ALS and the transcription factors junB and c-fos in a myeloid leukemia cell (PubMed ID: 1373742) line was made through M-CSF." (PMID 22235301, 2012).
myocardial infarction (1 paper, 2023). Gross necrosis of the myocardium, as a result of interruption of the blood supply to the area, as in coronary thrombosis. "Interestingly, although the AP1 components JunB and Fosl1 are upregulated in adult zebrafish hearts after injury, the same is not true for adult mice after myocardial infarction." (PMID 38259319, 2023).
nonalcoholic fatty liver disease (1 paper, 2025). "Furthermore, JUNB significantly influences hepatic metabolism and might contribute to the pathogenesis of nonalcoholic fatty liver disease by modulating lipid synthesis and catabolism in hepatocytes." (PMID 40918148, 2025).
Osteopenia (1 paper, 2024). Osteopenia is a term to define bone density that is not normal but also not as low as osteoporosis. "It has been demonstrated that mice lacking JunB showed osteopenia due to cell-autonomous defects of osteoblasts and osteoclasts." (PMID 39458926, 2024).
osteopetrosis (1 paper, 2020). Osteopetrosis, also known as marble bone disease, is a descriptive term that refers to a group of rare, heritable disorders of the skeleton characterized by increased bone density on radiographs. "They describe the embryonic lethality of cJun, JunB and Fra-1 (showing they are indispensable) but KO of any AP-1 causes some detrimental effect such as osteopetrosis (cFos KO) or male sterility (JunD KO)." (PMID 32917236, 2020).
osteoporosis (1 paper, 2023). A condition of reduced bone mass, with decreased cortical thickness and a decrease in the number and size of the trabeculae of cancellous bone (but normal chemical composition), resulting in increased fracture incidence. "WWP1 plays a vital role in osteoporosis through ubiquitination and degradation of RUNX2 and JUNB and is a potential target of miR-142-5p during bone fracture healing." (PMID 38129384, 2023). "WWP1 inhibits the differentiation of mesenchymal stem cells (MSCs) into osteoblasts through ubiquitination and proteasomal degradation of JUNB and the lysosomal degradation of CXCR4 following induction by tumor necrosis factor (TNF), thereby promoting inflammation-mediated osteoporosis." (PMID 38129384, 2023).
ovarian tumors (1 paper, 2022). "Consistently with our observations, the publicly available clinical data in breast and ovarian tumors strengthens the idea that JUNB overexpression can contribute to tumor aggressiveness." (PMID 36494864, 2022).
periodontitis (1 paper, 2025). An acute or chronic inflammatory process that affects the tissues that surround and support the teeth. "Additional genes encoding FOS and JUN family members (JUNB, FOSB, FOSL1) were significantly downregulated in periodontitis." (PMID 41124422, 2025).
pituitary adenoma (1 paper, 2014). "BCL6 is essential in pituitary adenoma due to interactions with several factors, including STAT3, IL-6 and JUNB." (PMID 25360166, 2014). "The PPI network of the downregulated DEGs in pituitary adenoma exhibited centralization, and certain node proteins of the network, including EGR1, STAT3, JUNB and FOS, were the common transcription factors in cancer; the PPI network of upregulated DEGs was sparsely populated." (PMID 25360166, 2014).
prostate intraepithelial neoplasia (1 paper, 2024). A neoplastic proliferation of the epithelial cells that line the acini and the ducts of the prostate gland. "JUNB is a subunit of the AP-1 transcription factor complex and is reported to have tumor suppressive functions in prostate cancer by preventing progression of low-grade prostate intraepithelial neoplasia (PIN) to high-grade PIN lesions." (PMID 38317241, 2024).
psoriasis vulgaris (1 paper, 2022). Plaque psoriasis is the most common presentation of psoriasis. "Other studies indicate an anti-inflammatory role of the AP-1 subunits in cutaneous pathology; an abrogation of JunB/AP-1 in keratinocytes triggered chemokine and cytokine expression, and the Jun subunit expression was found downregulated in psoriasis vulgaris patients." (PMID 35805110, 2022).
sebaceous gland tumors (1 paper, 2018). "Furthermore, to determine whether these de novo sebaceous glands may in long term generate hair follicles or sebaceous gland tumors, we monitored JunB cKO wounds for 90 days." (PMID 30143626, 2018).